SARDH (sarcosine dehydrogenase)
Description:
Catalyzes the last step of the oxidative degradation of choline to glycine. Converts sarcosine into glycine.
Synonyms: DMGDHL1; SDH; BPR-2; SAR; SARD
Tractability: PROTAC: ubiquitination databases record sites on it; its protein half-life has been measured.
Gene: Protein-coding gene on chromosome 9 (133,663,528 to 133,739,976, reverse strand). Ensembl gene ENSG00000123453.
Subcellular location: Mitochondrion matrix
Subcellular location (Human Protein Atlas): Mitochondria
Pathways (Reactome):
Metabolism: Choline catabolism
Gene Ontology:
Molecular function: sarcosine dehydrogenase activity
Cellular component: mitochondrion; cytoplasm; mitochondrial matrix
Genetic constraint (gnomAD): Loss-of-function variants: 92 observed, 100.58 expected, observed/expected ratio (o/e) 0.91, 90% interval 0.77 to 1.09. The upper end of that interval is the gene's LOEUF score, 1.09, which puts it in group 4 of 6, group 1 being the genes least tolerant of losing a copy. Missense variants: 1,265 observed, 1,265.3 expected, observed/expected ratio (o/e) 1, 90% interval 0.95 to 1.05. Synonymous variants: 572 observed, 522.73 expected, observed/expected ratio (o/e) 1.09, 90% interval 1.02 to 1.17.
Gene-disease validity (ClinGen):
ClinGen rates the evidence that SARDH causes each of these diseases.
sarcosinemia (autosomal recessive): Limited. Sarcosinemia is a metabolic disorder characterized by an increased concentration of sarcosine in plasma and urine due to sarcosine dehydrogenase deficiency.
Homologues: Orthologues: chimpanzee SARDH (99% identical), macaque SARDH (98% identical), dog SARDH (91% identical), pig SARDH (90% identical), rat Sardh (89% identical), mouse Sardh (89% identical), guinea pig SARDH (87% identical), tropical clawed frog sardh (80% identical), zebrafish sardh (77% identical), Drosophila melanogaster Sardh (49% identical). Paralogues in human: DMGDH (31% identical), PDPR (31% identical), AMT (12% identical), FOXRED1 (11% identical), L2HGDH (10% identical), YPEL3 (5% identical), YPEL4 (4% identical), YPEL2 (4% identical), YPEL1 (4% identical), YPEL5 (3% identical).
Diseases named in the same sentence as SARDH in open-access papers:
SARDH is named in the same sentence as 27 diseases in open-access papers, as found by Europe PMC text mining. Sharing a sentence is not in itself a finding about the gene and the disease. The quoted sentences say what the papers report.
prostate carcinoma (7 papers, 2013 to 2025). A carcinoma that arises from epithelial cells of the prostate gland. "A manual survey of the five articles suggested the role of sarcosine dehydrogenase in prostate cancer." (PMID 35208208, 2022). "TMEFF2 and SARDH cooperate to modulate one-carbon metabolism and the invasion of prostate cancer cells." (PMID 31552180, 2019). "Additionally, overexpression of SARDH in prostate cancer models has been shown to inhibit tumor growth." (PMID 40313243, 2025). "Our earlier studies revealed that the metabolite sarcosine and its biosynthetic enzyme, glycine N-methyltransferase (GNMT) were elevated in prostate cancer, while sarcosine dehydrogenase (SARDH) and pipecolic acid oxidase (PIPOX) that metabolize sarcosine, were reduced in prostate tumors." (PMID 26140362, 2015). "Therefore, the interaction of TMEFF2 with SARDH further suggests a role for TMEFF2 in prostate cancer progression." (PMID 23405127, 2013). "The low expression of SARDH suggested a worse prognosis in HCC, as well as in other cancers like prostate cancer, colorectal cancer and renal cell carcinoma 17-19." (PMID 38164283, 2024). "Treatment of prostate cancer cell lines with androgens resulted in an increase in GNMT expression and a simultaneous decrease in SARDH levels." (PMID 23405127, 2013).
sarcosinemia (4 papers, 2018 to 2025). "In this study, we addressed the relationship between formaldehyde metabolism and cognitive disorders in children with sarcosinemia, AD dementia patients, and mice deficient in either SARDH (Sardh−/−) or ALDH2 (Aldh2−/−)." (PMID 31815201, 2019). "Mutations in the gene encoding sarcosine dehydrogenase (SARDH) are associated with an autosomal recessive disorder—sarcosinemia (OMIM 268900)—which is manifested by elevated levels of sarcosine in blood and urine." (PMID 30467297, 2018). "A deficiency in sarcosine dehydrogenase results in a condition known as sarcosinemia." (PMID 40313243, 2025). "In addition, brain formaldehyde deficiency in sarcosinemia children associated with SARDH mutation or in Sardh−/− mice also led to cognitive deficits by reducing NMDA currents." (PMID 31815201, 2019). "These are the associations MCCC2—hydroxyvalerylcarnitine (3-methylcrotonylglycinuria), ETFDH—hexanoylcarnitine (glutaric acidemia type II) and SARDH—sarcosine (sarcosinemia)." (PMID 35888728, 2022). "Further, sarcosinemia patients exhibited lower SARDH activity in blood and lower formaldehyde concentrations in urine than age-matched healthy controls." (PMID 31815201, 2019). "The third variant rs10993780 is a common intron variant in SARDH with 136 homozygous healthy carriers in our cohort, which indicates that it is not causal for sarcosinemia." (PMID 35888728, 2022).
prostate neoplasm (2 papers, 2015 to 2022). A neoplasm (disease) that involves the prostate gland. "The two examples demonstrated that this method could produce useful MeSH terms of responsible enzymes and signal transduction pathways such as “Sarcosine Dehydrogenase” from sarcosine and prostate neoplasm and “Mechanistic Target of Rapamycin Complex 1” from leucine and diabetes mellitus, type 2." (PMID 35208208, 2022).
breast carcinoma (1 paper, 2014). "We analyzed the expression of GNMT, SARDH, and PIPOX in a tissue microarray of 721 breast cancer cases using immunohistochemistry (IHC)." (PMID 24884785, 2014). "Expression of sarcosine metabolism-related proteins differed significantly according to breast cancer subtype (GNMT, p = 0.005; SARDH, p = 0.012; tumoral PIPOX, p = 0.008; stromal PIPOX, p < 0.001)." (PMID 24884785, 2014). "Moreover, analysis of sarcosine metabolism phenotype revealed that patients with sarcosine-high type [GNMT(+)/SARDH and PIPOX(-)] tumors had a shorter DFS than patients with other breast cancer tumor types, suggesting that sarcosine level is a prognostic factor in breast cancer." (PMID 24884785, 2014). "Although we did not measure sarcosine levels directly from breast cancer tissues, we used expression levels of the major sarcosine metabolism-related proteins GNMT, SARDH, and PIPOX as surrogate for sarcosine level." (PMID 24884785, 2014).
breast tumours (1 paper, 2019). "Noteworthy, it has been found that human epidermal growth factor‐2 (HER‐2)‐positive breast tumours display upregulation of sarcosine metabolism‐related enzymes (GNMT, SARDH, PIPOX)." (PMID 30628163, 2019).
cognitive disorder (1 paper, 2019). A disease affects cognitive processes. "We also find that formaldehyde deficiency caused by mutation of the mitochondrial SARDH gene in children with sarcosinemia or in mice with Sardh deletion leads to cognitive deficits." (PMID 31815201, 2019). "Thus, SARDH mutation-induced formaldehyde deficiency may be related with human cognitive impairments." (PMID 31815201, 2019).
glioblastoma (1 paper, 2025). The most malignant astrocytic tumor (WHO grade IV). "This study identified six PMRGs (SARDH, ACHE, ADSL, PNPLA3, MAPK1 and SREBF2) as potential prognostic biomarkers for glioblastoma." (PMID 40313243, 2025).
glioma (1 paper, 2022). A benign or malignant brain and spinal cord tumor that arises from glial cells (astrocytes, oligodendrocytes, ependymal cells). "The staining figures revealed that the protein levels of SARDH and PSPH were higher in high-grade gliomas compared to low-grade gliomas, which was consistent with the results of the univariate analysis." (PMID 36467068, 2022). "Further univariate analysis demonstrated that SHMT1, SARDH, and PSPH were hazardous prognostic factors for glioma." (PMID 36467068, 2022).
hepatocellular carcinoma (1 paper, 2024). A malignant tumor that arises from hepatocytes. "This study was aimed to investigate the prognostic value and clinical significance of sarcosine dehydrogenase (SARDH) in hepatocellular carcinoma (HCC) and to explore the underlying mechanisms." (PMID 38164283, 2024).
migraine (1 paper, 2017). "Significant associations were also found between the NEMP gene SARDH (P = 0.000808) and migraine susceptibility providing evidence that genetic variation in nuclear encoded genes which are mitochondrially expressed may play an important role in migraine." (PMID 28361102, 2017). "The replication study supported significant association with the genes ELOVL6 (P = 0.00035), SARDH (P = 0.00081), and CSNK1G3 (P = 0.00037) and migraine." (PMID 28361102, 2017). "After applying a Bonferroni correction, three SNPs located in ELOVL6, SARDH and CSNK1G3 pass the significance threshold suggesting a particularly important role for these genes in migraine susceptibility." (PMID 28361102, 2017).
renal cell carcinoma (1 paper, 2024). "While SARDH methylation has not yet been explored in the context of in HCC, it has been studied in renal cell carcinoma." (PMID 38164283, 2024).
Sepsis (1 paper, 2022). Sepsis is defined as life-threatening organ dysfunction caused by a dysregulated host response to infection. "Given that sepsis dysregulates glycine metabolism in mice, we examined whether DCA might blunt glycine deficiency during sepsis by assessing GNMT, SARDH, SHMT1, and SHMT2, the key enzymes involved in glycine metabolism." (PMID 35730570, 2022).
tumor (11 papers, 2013 to 2025). "Recent studies have linked SARDH methylation to tumor growth and invasion." (PMID 40313243, 2025). "To explore the impact of SARDH on T-cell migration within the tumor microenvironment, we employed three-dimensional tumor spheroid models using ovalbumin-positive MC38 (MC38-OVA) and LLC-OVA cell lines." (PMID 40830700, 2025). "To further assess the impact of SARDH on T-cell function and its potential to impair tumor control, we conducted experiments using both systemic and conditional SARDH knockout OT-1+ mice that specifically recognize MC38-OVA." (PMID 40830700, 2025). "OT-1+ CD8+ T cells derived from both wild-type (WT) and SARDH knockout (SARDH−/−) OT-1+ mice were introduced into these tumor spheroids." (PMID 40830700, 2025). "In a model that more closely mimics the tumor microenvironment, where the proportion of tumor-reactive T cells in the peripheral blood is lower, we still observed that knocking down SARDH enhanced T-cell infiltration, as expected." (PMID 40830700, 2025). "Upon the knockdown of SARDH in these T cells, we observed an increase in T-cell infiltration into human cell line-derived tumor spheroids." (PMID 40830700, 2025). "In contrast, the expression levels of PNPLA3 and SARDH were significantly elevated in the tumor group compared to the control group, while ADSL expression was notably reduced in tumor tissues." (PMID 40313243, 2025). "These alterations induced by SARDH knockout in CD8+ T cells partially contributed to the enhanced tumor control ability." (PMID 40830700, 2025). "The importance of SARDH, and more extensively, 1-C metabolism in tumor-infiltrating T cells, was previously underappreciated." (PMID 40830700, 2025). "Silencing of SARDH significantly enhanced T-cell migration through the Matrigel layer, a substrate that mimics the tumor matrix." (PMID 40830700, 2025). "In summary, our findings underscore the critical role of SARDH in regulating T-cell migration and infiltration into tumor sites, ultimately dampening its efficacy in tumor suppression." (PMID 40830700, 2025). "SARDH, a mitochondrial flavoenzyme, plays an important role in one-carbon (1-C) metabolism, which appears to be reprogrammed in both tumor and infiltrating T cells." (PMID 40830700, 2025). "Compared with WT CD8+ T cells, SARDH−/− CD8+ T cells exhibited greater infiltration into the tumor spheroids in both the MC38- and LLC-derived spheroid models." (PMID 40830700, 2025). "Pan-cancer analysis from TCGA and GTEx databases revealed remarkable differences in SARDH expression across 27 tumor tissues." (PMID 38164283, 2024). "We have previously demonstrated that the tumor suppressor ability of TMEFF2 partly correlates with its ability to interact with SARDH and modulate the levels of sarcosine." (PMID 23405127, 2013). "In fact, we have also established that full-length TMEFF2 functions as a tumor suppressor and that this role correlates, at least in part, with its ability to interact with SARDH and modulate the cellular levels of sarcosine." (PMID 23405127, 2013). "We analyzed the tumor progression rates of subcutaneous MC38-OVA in SARDH−/− OT-1+ mice." (PMID 40830700, 2025). "TCR-T cells with reduced SARDH levels exhibited enhanced inhibition of A375 tumor progression." (PMID 40830700, 2025). "SARDH significantly impacts T-cell fate and function, leading to impaired tumor control efficacy." (PMID 40830700, 2025). "The upstream metabolic pathways related to SARDH, such as the methionine cycle and folate one-carbon metabolism, were systemically dysregulated in tumor-infiltrating T cells, suggesting that 1-C metabolism was reprogrammed during the adaptation of T cells in the TME." (PMID 40830700, 2025). "Given that SARDH has detrimental effects on T-cell effectiveness and exacerbates tumor malignancy, targeting SARDH as a metabolic checkpoint in T cells could be a promising anticancer strategy." (PMID 40830700, 2025).
tumor (continued). "We further generated human cell line-derived tumor spheroids from MART-1+ A375 cells and incubated them with MART-1-specific TCR-T cells to investigate the role of SARDH in human T-cell infiltration." (PMID 40830700, 2025). "qRT-PCR validation showed up-regulation of PNPLA3 and SARDH, and down-regulation of ADSL, in tumor tissues." (PMID 40313243, 2025). "In addition, qRT -PCR validation revealed significant differences in the expression of PNPLA3, SARDH, and ADSL in the control and tumour groups." (PMID 40313243, 2025). "It is also specific for the VAV2 locus, because the two genes that flank the VAV2 gene (SARDH, BRD3) do not show any consistent variation in expression in the human and mouse tumor datasets interrogated in this study." (PMID 32963234, 2020).
cancer (4 papers, 2020 to 2025). A tumor composed of atypical neoplastic, often pleomorphic cells that invade other tissues. "We established a computational screening pipeline focused on mitochondria-related genes and identified sarcosine dehydrogenase (SARDH) as a potential key regulator of T-cell mitochondrial metabolism in multiple cancer types." (PMID 40830700, 2025). "Our results underscore the dysregulation of 1-C metabolism within tumors and the detrimental impact of SARDH on T-cell fate and functions, suggesting new avenues for therapeutic interventions in cancer treatment." (PMID 40830700, 2025). "Overall, our study emphasized the potential therapeutic implications of targeting SARDH in T-cell-based cancer immunotherapy." (PMID 40830700, 2025). "Notably, SARDH was upregulated in exhausted CD8+ T cells across all cancer types and displayed a robust correlation with exhaustion markers, outperforming most other mitochondria-related genes." (PMID 40830700, 2025). "Collectively, these results suggest that targeting SARDH could serve as a potential target to increase the efficacy of T-cell-based cancer therapies." (PMID 40830700, 2025). "The pan-cancer analysis revealed that SARDH was significantly downregulated in 27 malignant tumors compared to their corresponding normal tissues, suggesting that SARDH may function as an oncogene." (PMID 38164283, 2024). "To assess the clinical potential of targeting SARDH in TCR-T-cell therapy, which holds significant promise in cancer treatment, we established a cell-derived xenograft model by inoculating MART-1+ A375 cells into NOD." (PMID 40830700, 2025). "To further corroborate these findings, we interrogated the RNA-seq data from the Cancer Cell Line Encyclopedia (CCLE) database and observed that SARDH, PIPOX, and GNMT, which are responsible for the conversion between glycine and sarcosine, were scarcely expressed in commonly used LUAD cell lines." (PMID 40275333, 2025). "CUVs from the genes MYO1E, SARDH and ISLR appeared in two distinct individuals with cancer from this non-Caucasian cohort, while CUVs from PCDHB16 and known CPG BMPR1A appeared in a single individual with cancer." (PMID 32778766, 2020).
SARDH also shares sentences with these, for which no sentence is quoted: colorectal cancer (2 papers); amnesia (1); co-infection (1); diabetes mellitus (1); glutaric acidemia type II (1); glutaric aciduria (1); Hepatic steatosis (1); hyperalaninemia (1); infection (1); Methylmalonic aciduria (1); Obesity (1); pyruvate carboxylase deficiency (1); type 2 diabetes (1).